KLK7 (kallikrein related peptidase 7)
Diseases named in the same sentence as KLK7 in open-access papers (continued):
Sharing a sentence is not in itself a finding about the gene and the disease.
thyroid cancer (5 papers, 2018 to 2025). "Although alterations in the mRNA, and protein levels of KLK7 have been observed in thyroid cancer, the specific mechanisms by which these changes influence thyroid cancer development, particularly in PTC, remain poorly understood." (PMID 39991575, 2025). "Immunohistochemistry findings also indicated that KLK7 protein levels are strongly correlated with the clinical stage and lymph node metastasis in thyroid carcinoma patients." (PMID 39991575, 2025). "The results of these experiments indicate that KLK7 protein and mRNA levels are elevated in advanced thyroid cancer, suggesting that KLK7 could be a potential therapeutic target for this stage of the disease." (PMID 39991575, 2025). "In addition, overexpression of NEAT1 is correlated with thyroid cancer progression by sponging miR214 and downregulation of NEAT1 is associated to suppression of PTC progression via the miR1295p/KLK7 axis." (PMID 32760219, 2020). "Overexpression of KLK7 is also closely related to poor prognosis in thyroid cancer." (PMID 32596158, 2020). "Thyroid carcinoma had three KLKs (KLK2: 0.943, KLK4: 0.914, KLK15: 0.905) that had AUC values above 0.90 threshold and KLK7 had an AUC of 0.910 in Chromophobe renal cell carcinoma." (PMID 29707153, 2018). "The addition of the shKLK7+EGF group further validated that KLK7 may function as an upstream regulator of EMT, facilitating thyroid cancer cell metastasis by promoting the MAPK/ERK signaling pathway and coordinating the EMT process." (PMID 39991575, 2025).
Alzheimer disease (4 papers, 2018 to 2025). A progressive, neurodegenerative disease characterized by loss of function and death of nerve cells in several areas of the brain leading to loss of cognitive function such as memory and language. "KLK7 peptidase is involved in skin shedding, cancer and Alzheimer’s disease progression." (PMID 36768453, 2023). "Moreover, KLK7 ablation exacerbated amyloid deposits in a mouse model of Alzheimer’s disease supporting the idea that KLK7 is a major peptidase involved in the degradation and clearance of deposited Aβ species." (PMID 32655372, 2020). "Besides all the information referring to KLK6 and KLK8, such as their aberrant expression in Alzheimer’s disease and dementia, a recent study expanded the KLKs contribution in CNS disorders by showing that the brain of Alzheimer’s disease patients presents decreased KLK7 mRNA expression." (PMID 32655372, 2020). "In Alzheimer’s disease (AD), KLK6-8 and 10 have been suggested as AD biomarker candidates, with CSF studies indicating elevated KLK6 and KLK10 in biomarker-confirmed cases, while KLK8 remains largely unchanged and KLK7 is decreased." (PMID 41516101, 2025). "Also, KLK7 is expressed in neurons and glia, participates in ECM turnover, and can directly cleave the plaque-forming amyloid-β (Aβ) peptides of 36 to 43 residues length, which potentially supports neuroprotection and prevents Alzheimer’s disease (AD)." (PMID 41516101, 2025).
hepatocellular carcinoma (4 papers, 2018 to 2024). A malignant tumor that arises from hepatocytes. "Prior studies have implicated these TRIP13 targets in the progression of various cancers, including COL6A3 and KLK7 in CRCs, SHC3 in hepatocellular carcinomas, and TREM2 in gastric cancers and renal cell carcinomas." (PMID 33037736, 2020). "COL6A3 and KLK7 in CRCs, SHC3 in hepatocellular carcinomas, and TREM2 in gastric cancers and renal cell carcinomas are associated with tumor growth." (PMID 33037736, 2020). "However, the expression level of KLK7 had no such elevation in hepatocellular carcinoma tissues as control." (PMID 29560118, 2018).
Hyperkeratosis (4 papers, 2014 to 2021). Hyperkeratosis is a histopathological term defining a thickened stratum corneum and may be present in many different skin conditions, with many possible overlaps. "Hyperkeratosis in epidermis is thoroughly regulated by serine proteases such as KLK5 or KLK7 and serine protease inhibitors such as SPINK5." (PMID 33652999, 2021). "KLK7 was first identified as a protease involved in the desquamation process in the outermost layer of the skin and transgenic mice overexpressing human KLK7 display hyperkeratosis, epidermal thickness and cumulative appearances of immune cells in the dermis." (PMID 28932870, 2018). "Then, KLK5 and KLK7 induced proteolysis of desmocollin 1 (DSC-1), one of corneodesmosonal components, which is involved in hyperkeratosis." (PMID 33652999, 2021).
renal cell carcinoma (4 papers, 2018 to 2024). "In an earlier study using immunohistochemical analysis, KLK6 and KLK7 have been shown to have lower expression in high grade, in contrast to low grade renal cell carcinoma." (PMID 29707153, 2018). "In terms of renal cell carcinoma (RCC), clinical experimental studies have proven that some KLKs, such as KLK1, KLK3, KLK6, KLK7, and KLK15, are differentially expressed in different subtypes of RCC, and KLK6 has predictive value in RCC." (PMID 39116105, 2024).
pancreatic adenocarcinoma (3 papers, 2008 to 2024). "Moreover, recently we have further demonstrated that KLK7/hK7 is overexpressed in pancreatic adenocarcinomas." (PMID 19091121, 2008). "Additionally, expression of KLK7 in the human pancreatic adenocarcinoma cell line BxPC-3 significantly increased the amount of soluble desmoglein 2 shed from the cell surface, which correlates with the in vitro degradation data." (PMID 19091121, 2008).
prostate carcinoma (3 papers, 2017 to 2023). A carcinoma that arises from epithelial cells of the prostate gland. "In pancreatic cells, KLK7 induced shedding of E‐cadherin and induced EMT in prostate cancer associated with a remarkably increased cell migration and invasion." (PMID 28636767, 2017). "However, it was reported that Kallikrein-related peptidase 7 was down-regulated in prostate cancer, indicating that inhibition of KLK7 may influence the normal function of prostate, but this needs further investigations." (PMID 29560118, 2018).
Pruritus (3 papers, 2016 to 2019). Pruritus is an itch or a sensation that makes a person want to scratch. "Moisturizing the skin can improve skin barrier function by reducing KLK7 expression and thus effectively alleviate pruritus." (PMID 31118960, 2019).
serous ovarian cancer (3 papers, 2019 to 2020). "KLK7 was found to be increased in four various cancer data sets compared with healthy tissues including ovarian serous adenocarcinoma and ovarian endometrioid adenocarcinoma." (PMID 33336051, 2020). "KLK7 mRNA expression levels were measured in 139 cases of advanced high-grade serous ovarian cancer tissues." (PMID 33087135, 2020). "mRNA expression levels of KLK7 were quantified by qPCR in a well-characterized patient cohort afflicted with advanced high-grade serous ovarian cancer (FIGO III/IV, n = 139)." (PMID 33087135, 2020). "Finally, increased KLK7 protein levels have been detected in sera of serous ovarian cancer patients compared to healthy controls suggesting it as a liquid biopsy early detection biomarker." (PMID 33087135, 2020). "Therefore, it is not too surprising that we observed indication for coordinate expression of some KLKs such as KLK6/KLK8 (Spearman correlation of mRNA levels: rs = 0.636;), KLK10/KLK11 (rs = 0.647;), or KLK5/KLK7 (rs = 0.568; unpublished results) in advanced high-grade serous ovarian cancer." (PMID 30811511, 2019).
amyloid (2 papers, 2018 to 2026). "KLK7 mRNA level was significantly reduced in AD brain, and genetic ablation of KLK7 in AD model mice exacerbated the amyloid pathology." (PMID 29311134, 2018). "Collectively, these results indicate that Klk7 is a crucial component of brain Aβ economy and attenuates brain amyloid pathology in AD model mice." (PMID 29311134, 2018). "In this manuscript, we have investigated the pathophysiological impact of KLK7 in brain Aβ economy and identified KLK7 as the astrocyte‐derived Aβ‐degrading enzyme that regulates amyloid pathology in vivo." (PMID 29311134, 2018).
breast invasive carcinoma (2 papers, 2018 to 2023). "Five KLKs were commonly downregulated in head-neck squamous cell carcinoma and breast invasive carcinoma: KLK3 (3-fold and 4-fold), KLK6 (2-fold and 6-fold), KLK7 (2-fold and 10-fold), KLK11 (5-fold and 6-fold) and KLK13 (8-fold and 3-fold)." (PMID 29707153, 2018).
cutaneous melanoma (2 papers, 2011 to 2017). A primary melanoma arising from atypical melanocytes in the skin. "Interestingly, changes in the KLK6 and KLK7 expression profile were associated with the transition from thin to thick cutaneous melanomas, being also significantly correlated to other genes functionally related to keratinocyte differentiation, cell shedding, invasion, and migration." (PMID 22032772, 2011). "In concordance with our findings, a previous gene expression study revealed that KLK7, KLK4, and KLK11 expression is correlated with metastatic dissemination and associated with overall survival of patients with primary cutaneous melanoma." (PMID 28636767, 2017). "Therefore, KLK7 might be considered as a potential progression marker for skin melanoma." (PMID 28636767, 2017).
esophageal adenocarcinoma (2 papers, 2016 to 2017). A malignant tumor with glandular differentiation arising predominantly from Barrett mucosa in the lower third of the esophagus. "Xi and colleagues (2015) elegantly demonstrated that miR-217 is downregulated and that its target gene, kallikrein 7 (KLK7), increases in esophageal adenocarcinoma cell lines and esophageal tumors that have been exposed to cigarette smoke condensate (CSC)." (PMID 28025544, 2016).
glioblastoma (2 papers, 2009 to 2015). The most malignant astrocytic tumor (WHO grade IV). "Moreover, we have shown that U-251-MG glioblastoma cells transfected with KLK7 showed increased invasive potential in an in vitro Matrigel assay." (PMID 19367279, 2009).
glioma (2 papers, 2015 to 2019). A benign or malignant brain and spinal cord tumor that arises from glial cells (astrocytes, oligodendrocytes, ependymal cells). "KLK7 overexpression increases cell invasion in glioma cell lines in vitro matrigel assay." (PMID 26231762, 2015). "The current work therefore points to the need for additional studies to determine the potential pathophysiological roles of KLK7 and KLK9 in glioma malignancy and any parallel involvement of PAR-activation in mediating their effects." (PMID 26231762, 2015). "The kallikreins KLK6, KLK7, and KLK9 have been shown to have higher protein levels in Grade IV glioma compared to Grade III tumours and consequently may have utility as prognostic markers for patient survival." (PMID 32082376, 2019).
head and neck squamous cell carcinoma (2 papers, 2014 to 2018). A squamous cell carcinoma that arises from any of the following anatomic sites: lip and oral cavity, nasal cavity, paranasal sinuses, pharynx, larynx, and salivary glands. "Correlative studies have already provided evidence that five other protein members of KLK family (KLK4, KLK5, KLK7, KLK8, and KLK10) were abundantly expressed in head and neck squamous cell carcinoma, showing diagnostic value." (PMID 24669031, 2014).
lymph node metastasis (2 papers, 2023 to 2025). "KLK7 was upregulated in PTC tissues and positively associated with clinical stage and lymph node metastasis." (PMID 39991575, 2025). "This research employed public databases and immunohistochemical tissue microarrays from cancer specimens to examine the differential expression levels of KLK7 in malignant versus healthy tissues, revealing its significance for clinical staging and lymph node metastasis." (PMID 39991575, 2025).
renal carcinoma (2 papers, 2011 to 2021). A carcinoma arising from the epithelium of the renal parenchyma or the renal pelvis. "KLK expression is cell- and tissue-dependent, and although KLK6 and KLK7 have been suggested to promote tumor cell invasion, loss of KLK5 has been observed in prostate, lung, breast, testicular, and renal cancer tissues versus their normal counterparts, similar to our PDAC data presented herein." (PMID 22203845, 2011).
alopecia (1 paper, 2017). Hair loss usually from the scalp. "Nevertheless, Klk5-/-Klk7-/-Sp5A135X/A135X showed alopecia and growth retardation 2–4 weeks after birth, which disappeared with age." (PMID 28095415, 2017).
astrocytoma (1 paper, 2015). "Through a comprehensive parallel analysis of immunoreactivity for six kallikreins in grade III and IV astrocytoma we determined that tumor core staining for KLK7 and KLK9, like KLK6, has significant prognostic value with regard to patient survival." (PMID 26231762, 2015). "Like KLK6, higher levels of KLK1, KLK7, KLK8, KLK9 and KLK10 were all found to be associated with higher astrocytoma grade." (PMID 26231762, 2015). "In this study we determined KLK1, KLK6, KLK7, KLK8, KLK9 and KLK10 protein expression in two independent tissue microarrays containing 60 grade IV and 8 grade III astrocytoma samples." (PMID 26231762, 2015). "Expression of KLK1, KLK6, KLK7, KLK8, KLK9 and KLK10 protein was assessed by immunohistochemical analysis of grade III (n = 8) and grade IV (n = 60, n = 55 for KLK1) astrocytoma samples." (PMID 26231762, 2015).
brain tumors (1 paper, 2015). "Both studies support the idea that KLK7 expression leads to more aggressive brain tumors." (PMID 26231762, 2015).
cancers of the oral cavity (1 paper, 2024). "However, an association between high KLK7 protein levels and adverse pathological features or poor clinical outcome of squamous cell carcinomas has been described in two other studies on 30 and 80 cancers of the oral cavity." (PMID 38961454, 2024).
carcinoma in-situ (1 paper, 2026). "We found that upregulation of KLK7 and KLK10 RNA and protein occurs early in tumor development and marks carcinoma in-situ lesions (stage 0, PanIN3) and early-stage (stage 1) PDAC, while non-cancerous low grade lesions stain negative for these proteases." (PMID 41974993, 2026).
cervical tumors (1 paper, 2008). "Consistent with our findings, it has been observed that KLK7 expression is up-regulated in cervical tumors as well as in cells lines derived from them." (PMID 18588690, 2008).
chromophobe renal cell carcinoma (1 paper, 2018). Chromophobe renal cell carcinoma is a rare subtype of renal cell carcinoma, originating from the intercalating cells of the collecting ducts and macroscopically manifesting as a well-circumscribed, highly lobulated, solid tumor that is usually diagnosed at an early stage. "Chromophobe renal cell carcinoma had increased expression of the following KLKs: KLK1 (32-fold), KLK2 (12-fold), KLK3 (69-fold), KLK4 (234-fold), KLK15 (132-fold), whereas decreased expression of KLK5 (5-fold), KLK6 (13-fold), and KLK7 (26-fold)." (PMID 29707153, 2018).
clear cell renal cell carcinoma (1 paper, 2018). "The renal papillary carcinoma and renal clear cell carcinoma had dramatically decreased expression of KLK1 (52-fold and 94-fold), KLK6 (45-fold and 42-fold) and KLK7 (33-fold and 48-fold), respectively." (PMID 29707153, 2018).
dementia (1 paper, 2018). Loss of intellectual abilities interfering with an individual's social and occupational functions. "Finally, we found that the Food and Drug Administration‐approved anti‐dementia drug memantine can increase the expression of Klk7 and Aβ degradation activity specifically in the astrocytes." (PMID 29311134, 2018).
epidermal cyst (1 paper, 2023). "Collagen XVII and P-cadherin are increased but Klk7 is decreased in the epidermal cyst in the PKC inhibition group compared to that of the control group at D2 and D3." (PMID 37996466, 2023).
esophageal cancer (1 paper, 2021). A primary or metastatic malignant neoplasm involving the esophagus. "In esophageal cancer, this miRNA was found to be repressed after exposure of cells to cigarette smoke condensate, which in turn resulted in overexpression of miR-217-5p’s direct target, kallikrein 7 (KLK7), which induced growth and invasiveness of cancer cells." (PMID 34439138, 2021).
esophageal squamous cell carcinoma (1 paper, 2017). Esophageal squamous cell carcinoma (ESCC) is a type of esophageal carcinoma (EC) that can affect any part of the esophagus, but is usually located in the upper or middle third. "In esophageal squamous cell carcinoma cells, miR-217 inhibits proliferation, migration, and invasion by targeting long noncoding RNA MALAT1 and kallikrein 7 (KLK7)." (PMID 28437471, 2017).
gallbladder carcinoma (1 paper, 2024). "Our data suggest that ovarian, endometrial, pancreatic, and gallbladder carcinomas might represent suitable tumor entities for clinical trials once anti-KLK7 drugs will move towards testing in human patients." (PMID 38961454, 2024).
hypospadias (1 paper, 2020). Hypospadias is the displacement of the urethral meatus on the ventrum of the penis. "This region on chromosome 19 is characterized by clusters of sialic acid-binding Ig-like lectin (SIGLEC) and kallikrein (KLK) genes, among which we identified likely causal relationships with hypospadias (CD33/SIGLEC3, SIGLEC5, SIGLEC7, KLK5, KLK7, KLK10, KLK13, and KLK14)." (PMID 32728162, 2020).
influenza (1 paper, 2016). An acute viral infection of the respiratory tract, occurring in isolated cases, in epidemics, or in pandemics; it is caused by serologically different strains of viruses (influenzaviruses) designated A, B, and C, has a 3-day incubation period, and usually lasts for 3 to 10 days. "Of the proteins with reduced expression identified in our study, the five most-reduced DEPs in samples from influenza-infected patients that were also correlated with higher viral loads were CTSD, KLK7, MFGE8, MAPK9 and CD27, respectively." (PMID 27088501, 2016).
kidney tumors (1 paper, 2017). "Interestingly, KLK7 has been found to be a useful biomarker to distinguish various types of kidney tumors when morphology is similar." (PMID 28636767, 2017).
oral carcinomas (1 paper, 2025). "In HSIL samples, we found significant overexpression of KLK5, KLK7 and their inhibitor LEKTI, which is consistent with reports in other cancers, such as colon and oral carcinomas." (PMID 40753921, 2025).
ovarian serous cystadenocarcinoma (1 paper, 2020). A malignant serous cystic epithelial neoplasm arising from the ovary. "Our analytical mining of the UALCAN database indicated that the expression level of KLK7 was higher in stage 4 compared with stages 2 and 3 of ovarian serous cystadenocarcinoma (P < 0.05) for cancer stages." (PMID 33336051, 2020). "We next concentrated on the detection of KLK7 expression in normal and ovarian serous cystadenocarcinoma samples using UALCAN database." (PMID 33336051, 2020).
Parkinson disease (1 paper, 2020). A progressive degenerative disorder of the central nervous system characterized by loss of dopamine producing neurons in the substantia nigra and the presence of Lewy bodies in the substantia nigra and locus coeruleus. "The dysregulation of certain KLKs, that is, KLK1 and KLK7, but mainly KLK6 and KLK8, may contribute to the development of neurodegenerative or neurological disorders such as Alzheimer’s and Parkinson’s diseases, memory disorders or mental illness." (PMID 32655372, 2020).
Peritoneal Cancer (1 paper, 2025). A peritoneum cancer that is located in the inside of the abdomen. "In xenograft models, KLK7-overexpressing cells increased PM and exhibited higher Peritoneal Cancer Index (PCI) scores compared to controls." (PMID 41335524, 2025).
prostatitis (1 paper, 2022). An infectious or non-infectious inflammatory process affecting the prostate gland. "Studies have shown that KLK7 is involved in the progression of multiple systemic diseases, including skin diseases, tumors, and prostatitis." (PMID 35873711, 2022).
salivary gland diseases (1 paper, 2023). "Further exploration of the inhibitory effect of testosterone on Klk6 and Klk7 expression, and their potential impact on susceptibility to salivary gland diseases, also warrants careful consideration in future studies." (PMID 38203721, 2023).